CD14 (CD14 molecule)
Diseases named in the same sentence as CD14 in open-access papers (continued):
Sharing a sentence is not in itself a finding about the gene and the disease.
myocardial infarction (30 papers, 2012 to 2025). Gross necrosis of the myocardium, as a result of interruption of the blood supply to the area, as in coronary thrombosis. "Specifically, increased levels of cystatin C, serpin F2, and CD14 were correlated with an increased risk of myocardial infarction, vascular events, and mortality." (PMID 37293281, 2023). "This SNP was shown to be functional and increase the transcriptional activity of CD14, which leads to higher (m)CD14 protein levels and an increased risk of myocardial infarction." (PMID 31671579, 2019). "In risk stratification, proteins including CD14—associated with myocardial infarction risk—and HP—linked to lipid metabolism—could be incorporated into a multi-marker panel to improve identification of high-risk individuals." (PMID 41283645, 2025). "Thus, in patients with acute myocardial infarction, peak levels of the classical CD14++CD16− monocytes have been inversely associated with the magnitude of myocardium salvaged as well as with the recovery of left ventricular function." (PMID 39273110, 2024). "Notably, a less marked decrease in the CD14++CD16+ monocytes levels at the first month following acute myocardial infarction has been associated with a better left ventricular EF after six months." (PMID 39273110, 2024). "Increased levels of cystatin C, serpin F2, and CD14 were correlated to an increased risk of myocardial infarction, vascular events and all-cause mortality, whereas increased levels of CD14 was also correlated to an increased risk of the occurrence of an ischemic stroke." (PMID 30186839, 2018). "Nine months after bare metal stent implantation after acute myocardial infarction, the number of CD14 + CD16 + CX3CR1 + monocytes in patients with restenosis was higher than that in patients without restenosis." (PMID 39820843, 2025). "Downregulation of miR-1 was also observed in CD14 positive monocytes in patients with acute myocardial infarction, at a stage with increased monocyte levels." (PMID 33584638, 2020). "Serum levels of zonulin, lipopolysaccharide and soluble CD14 (a protein that binds lipopolysaccharide) were measured in disease-free centenarians, young healthy controls and patients with precocious acute myocardial infarction." (PMID 29896420, 2018). "A positive correlation of 0.37 between CD14+ level and post-infarction cardiosclerosis (PIC) suggests an association between monocyte activity and the development of myocardial fibrotic changes after myocardial infarction." (PMID 40218200, 2025). "Interestingly, the numbers of both CXCR4+ and KDR+ monocytes increased after myocardial infarction, and their correlation with CD14++CD16+CCR2+ monocytes was more significant." (PMID 40079002, 2025). "A cross-sectional study investigated the impact of CD14++CD16+ monocytes on coronary plaques in patients with acute myocardial infarction showed that CD14++CD16+ monocytes were significantly more prevalent in patients with coronary plaque rupture than in those without plaque rupture." (PMID 28789689, 2017). "NEAT1 is significantly downregulated in the PMBCs of early-onset myocardial infarction (MI) patients, mainly in the cluster of differentiation-14-positive (CD14+) monocytes." (PMID 40362651, 2025). "Circulating CD14+HLA-DRneg/low monocytes secrete high levels of TNFα, IL-6, and IL-1β which promote proinflammatory immune responses; in the expansion of this monocyte population after myocardial infarction correlates with both cardiac damage and physiological function." (PMID 34589791, 2021). "We therefore measured serum zonulin, LPS and soluble CD14 (an acute phase protein that mediates immune responses to LPS) in disease-free centenarians (“dodgers”) and compared the results with young healthy controls and patients with precocious acute myocardial infarction (AMI)." (PMID 29896420, 2018).
myocardial infarction (continued). "Also, it was showed that the CD14+CD16+CX3CR1+monocytes might have a role in-stent restenosis following coronary implantation of bare-metal stents in patients with acute myocardial infarction." (PMID 27277665, 2016). "Elevated expression and activity of CD14, TLR2, and TLR4 correlate with advanced atherosclerotic lesions, followed by plaque rupture and myocardial infarction." (PMID 34829669, 2021). "After myocardial infarction, the monocyte subset (CD14++CD16−, CD14++CD16+, and CD14+CD16++) numbers in the circulation increase in patients with STEMI." (PMID 32676508, 2020). "In addition, CD14 could also be directly related to heart failure after myocardial infarction." (PMID 33574831, 2020). "FCN1, CD14, S100A9, ALDH2, hsa-let-7d, hsa-let-7b, hsa-miR-124-3, and hsa-miR-9-1 were identified as potential candidate regulators in acute myocardial infarction." (PMID 30886860, 2019). "Monocytes also infiltrate the heart following acute myocardial infarction, as shown by the increase in CD14+CD16- and CD14+CD16+ cells as compared to heart tissue from donors who died of other causes." (PMID 31456804, 2019). "The existence of FFAR2+ and FFAR3+ cells in human myocardial infarction tissue, by immunofluorescent co-staining for FFAR2/3 and canonical marker genes of monocytes and macrophages (CD14, CX3CR1, and CD68), indicating the existence of FFAR2/3 positive monocytes and macrophages." (PMID 40308581, 2025). "Moreover, it was reported that patients with restenosis presented a higher count of CD14+CD16+CX3CR1+ monocytes than patients without restenosis after 9 months of the implantation of the bare-metal stent as a result of acute myocardial infarction." (PMID 36741809, 2022). "In accordance with these studies, we also did not demonstrate a genetic influence of CD14 SNP rs2569190 on the incidence of cardiovascular preexisting conditions (stroke, myocardial infarction, and peripheral arterial disease) in the present European cohort of CV patients." (PMID 34305452, 2021).
type 2 diabetes (29 papers, 2012 to 2026). "In conclusion, the expression of IDOL in CD14+ monocytes was decreased in type 2 diabetes and was associated with glycemia and serum FGF21 concentration." (PMID 37094639, 2023). "In conclusion, the expression of IDOL in CD14+ monocytes was decreased in subjects with type 2 diabetes and was associated with glycemia and serum FGF21 concentration." (PMID 37094639, 2023). "The aim of this study was to evaluate the association of cystatin C, CD26, and CD14 proteins in serum exosomes from patients with Type 2 Diabetes (T2D), metabolic syndrome (MetS), and atherogenic index of plasma (AIP)." (PMID 35846887, 2022). "That FcR expression can differ between sex has previously been reported where CD14+ monocytes exhibited higher FcγRII levels in a cohort of female healthy and type 2 diabetes individuals compared to men." (PMID 38020313, 2023). "In a previous study, a herbal extract named Baihu decoction, which has hypoglycemic and antioxidant effects, significantly inhibited a CD14/TLR4/NF-kB pathway, and its associated inflammation, in a type 2 diabetic mouse model." (PMID 34829669, 2021). "The expression levels of TERC in CD14+ cells from type II diabetes and multiple sclerosis patients were significantly higher than normal people." (PMID 31294790, 2019). "(a) Flow cytometry analysis of Tim‐3 expression on CD14+ monocytes cells (left) and the statistical graph is shown (right) for type 2 diabetes patients (n = 31, 30.43 ± 3.58%) and healthy donors (n = 18, 50.78 ± 2.36%)." (PMID 30180306, 2018). "On a high-fat diet, CD14 expressed on both hematopoietic cells and adipocytes contributes to mesenteric fat accumulation and type-2 diabetes development." (PMID 23898465, 2013). "Whether the reduction in IDOL expression and the concomitant increase in intracellular lipid accumulation in CD14+ monocytes in type 2 diabetes has any adverse consequences is unclear." (PMID 37094639, 2023). "Furthermore, we cannot rule out the possibility that the differences in intracellular lipid accumulation in CD14+ monocytes seen in vivo may be a reflection of the dyslipidemia present in subjects with type 2 diabetes." (PMID 37094639, 2023). "Hence, this study aims to elucidate whether circulating monocyte subsets, especially CD14++CD16+ monocytes, are associated with serum fetuin-A levels and their related insulin resistance in patients with type 2 diabetes mellitus (T2D)." (PMID 29582352, 2018). "For the Type 2 diabetes candidate gene transcription factor 7-like 2 (TCF7L2) on chromosome 10q25.3, the methylation pattern is similar along the gene body but there are certain CpG sites that show unmethylated state in CD14+ monocytes only (see arrows)." (PMID 22848472, 2012). "However, even though a negative relation was observed between EV-CD14 and incident type 2 diabetes in this study, this does not necessarily imply a direct role for CD14 in reduced progression of development of type 2 diabetes." (PMID 24498934, 2014).
gastric cancer (27 papers, 2007 to 2026). A primary or metastatic malignant neoplasm involving the stomach. "Specifically, “CCR2 on CD14- CD16+ monocyte” was found to have a causal relationship with both stomach cancer and rectal cancer." (PMID 38533503, 2024). "As H. pylori infection is known to be the main risk factor for gastric cancer, we examined the potential interaction between H. pylori infection and CD14 -260C/T polymorphism in the development of gastric cancer." (PMID 24978812, 2014). "Association between TLR2, TLR4 and CD14 polymorphisms and risk of gastric cancer in ethnic Chinese individuals." (PMID 23565226, 2013). "Individual studies included in the meta-analysis of TLR2, TLR4 and CD14 polymorphisms and gastric cancer." (PMID 23565226, 2013). "Effect of Helicobacter pylori infection and TLR2, TLR4 and CD14 polymorphisms on gastric cancer risk." (PMID 23565226, 2013). "In particular, recent studies have observed that functional CD14 polymorphisms, especially in the promoter motifs, are associated with a higher risk of H. pylori-related gastric carcinoma." (PMID 23338226, 2013). "In addition to these risk factors, we also recently demonstrated that genetic variability in specific genes (e.g., MUC2, NFKB1 and CD14) is associated with the progression to gastric cancer from precursor lesions." (PMID 34199386, 2021). "This meta-analysis suggests that the CD14 -260C/T polymorphism may increase the risk of gastric cancer in H. pylori-infected individuals." (PMID 24978812, 2014). "In conclusion, this meta-analysis suggests that the CD14 -260C/T polymorphism may increase the risk of gastric cancer in H. pylori-infected individuals." (PMID 24978812, 2014). "However, there is little evidence regarding the cellular impact and associated molecular basis of CD14 on gastric carcinoma cells." (PMID 23338226, 2013). "In addition, in further subgroups analysis by Helicobacter pylori (H. pylori) infection status and tumor location in gastric cancer subgroup, we found that the CD14 -260C/T polymorphism may increase the risk of gastric cancer in H. pylori-infected individuals." (PMID 24978812, 2014). "However, it is important to recognize that the association between CD14 and gastric cancer risk may vary between ethnicities." (PMID 23338226, 2013). "CD14+ tumor-infiltrating macrophages expressing IL-10 have been found and enriched in gastric cancer patients to facilitate immune evasion." (PMID 40244064, 2025). "It is reported that plasma exosome proteins ILK1 and CD14 were correlated with organ-specific metastasis in patients with advanced gastric cancer." (PMID 40708696, 2025). "In our future study, the biological functions of ILK1 and CD14 in driving organ-specific metastasis in gastric cancer cells will be further investigated." (PMID 37568802, 2023). "Based on the obtained results, we noticed a statistically significant decrease in the percentage of NK cells CD3-CD16+CD56+ and classical monocytes CD14+CD16- in patients diagnosed with gastric cancer compared to patients in the control group." (PMID 36982898, 2023). "ILK1 and CD14 were correlated with organ-specific metastasis and participated in regulating biological behavior sin gastric cancer cells." (PMID 37568802, 2023). "In contrast, the overexpression of CD14 in gastric carcinoma cells has resulted in enhanced apoptosis and has antitumor potential." (PMID 37373173, 2023). "Concomitant with our findings, a poor prognosis and reduced survival of advanced gastric cancer are correlated with an increased CD33+CD11b+CD15+CD14-expressing PMN-MDSC infiltration." (PMID 34944780, 2021).
gastric cancer (continued). "We investigated the frequencies of TILs including CD8+ T cells, CD45+CD4+CD25± FOXP3+ Tregs, CD45+CD11b+ CD14+ HLA−DR− MDSCs in 28 gastric cancer tissues by using multicolor flow cytometry." (PMID 26799288, 2016). "In summary, we have provided experimental evidence to elucidate the tumor-suppressive role of CD14 in gastric cancer." (PMID 23338226, 2013). "Here, we investigate the effects of CD14 on gastric cancer cells using a gastric cancer cell line ectopically expressing CD14." (PMID 23338226, 2013). "PCR primer sequences and thermal conditions used for genotyping of CD14 and TLR2 polymorphisms in gastric cancer patients and functional dyspepsia controls." (PMID 23565226, 2013). "To determine the impact of CD-14 on the cellular behavior of gastric carcinoma cells, we established a SGC-7901 gastric cancer cell line stably overexpressing CD-14." (PMID 23338226, 2013). "We found that cells overexpressing CD-14 exhibited significantly (p < 0.05) reduced cell viability, suggesting that the CD-14-mediated inflammatory response diminishes the gastric cancer cell viability." (PMID 23338226, 2013). "Despite the epidemiological evidence, data regarding the impact of CD14 on gastric carcinoma cells has been rare." (PMID 23338226, 2013). "To address this question, we generated a CD14-overexpressing SGC-7901 gastric carcinoma cell line and analyzed the impact of CD14 expression." (PMID 23338226, 2013). "Increasing evidence has suggested that CD14 status significantly influences the clinical outcome of H. pylori infection, which can result in gastric carcinoma." (PMID 23338226, 2013). "In this study, we investigated the cellular impacts of CD14 on gastric carcinoma cells after MDP stimulation." (PMID 23338226, 2013). "CD-14 overexpression causes decreased clonogenic ability and cell viability in SGC-7901 gastric carcinoma cells." (PMID 23338226, 2013). "Genetic variability in CD14 may play a role in developing gastric cancer precursor lesions over time and in gastric carcinogenesis." (PMID 37071001, 2023). "The study found that biological functions of plasma exosome proteins among AGC patients with different metastatic modes were distinct, in which ILK1 and CD14 were correlated with organ-specific metastasis and participated in regulating malignant behaviors in gastric cancer cells." (PMID 37568802, 2023). "Therefore, it is crucial to gain more insight regarding the role of CD14 in gastric cancer progression." (PMID 23338226, 2013). "Therefore, we evaluated the impact of CD-14 on gastric cancer cell invasiveness by transwell invasion assays." (PMID 23338226, 2013). "In gastric cancer (GC), LPS binds to CD14, increasing cell viability and inflammatory factor production while inhibiting apoptosis." (PMID 40444051, 2025). "IL-35-producing B cells were also elevated in the peripheral blood of gastric cancer (GC) patients and were responsible for the accumulation of immune suppressive Treg cells, MDSCs, IL-10-producing B cells and CD14+ monocytes." (PMID 33418929, 2021). "Thus, we examined whether increased expression of CD-14 could activate NF-κB in gastric cancer cells." (PMID 23338226, 2013). "Gastric cancer tissues had reduced CD3+T, CD3+CD4+T cells and M1 macrophage infiltration, increased M2 macrophages and CD14+monocytes; AKAP12 was positively correlated with monocytes." (PMID 41798945, 2026). "Overexpression of CD14 and ILK1 impacted the colony formation ability of gastric cancer and increased expression of Vimentin." (PMID 37568802, 2023). "A number of studies relating to gastric cancer (GC) have reported MDSCs phenotype markers, including CD11b+, CD33+, CD14+, CD15+and HLA-DR-26,27." (PMID 32415175, 2020). "CD14 and C1QB were identified using the GO and KEGG analysis, and we further conducted prognosis analyses of these two genes in intestinal-type gastric cancer, as HPAG usually progresses into intestinal-type gastric cancer." (PMID 40092684, 2025).
gastric cancer (continued). "Based on public omics data, it was also found that some of these biomarkers showed significant changes in the progression from gastritis to dysplasia and gastric cancer, and were reported to participant in the progression of gastric cancer, such as LEP, CCL2, CD14 and TNF." (PMID 39367502, 2024). "Currently, the roles of ILK1 and CD14 in the plasma exosomes of gastric cancer patients have not been fully reported." (PMID 37568802, 2023). "Overexpression of CD14 and ILK1 could increase colony formation ability and expression of epithelial–mesenchymal transition (EMT) markers in gastric cancer cells." (PMID 37568802, 2023). "Here, our data confirms CD163 in gastric cancer has a positive correlation with Tregs (CD4, CD25 and FOXP3), MDSCs (CD33, CD11b and CD14) and Cafs (FAP), indicating CD163 level is an potential index to monitor the status of tumor associated macrophages, Tregs, MDSCs and Cafs in gastric cancer." (PMID 29152078, 2017). "In the present study, by establishing CD14- and ILK1-overexpressing gastric cancer cell models, the size of colonies was significantly increased more than in control cells, which suggested CD14 and ILK1 could promote outgrowth of metastasis in gastric cancer." (PMID 37568802, 2023).